POM121 (POM121 transmembrane nucleoporin)
Diseases named in the same sentence as POM121 in open-access papers:
POM121 is named in the same sentence as 37 diseases in open-access papers, as found by Europe PMC text mining. Sharing a sentence is not in itself a finding about the gene and the disease. The quoted sentences say what the papers report.
prostate carcinoma (7 papers, 2019 to 2025). A carcinoma that arises from epithelial cells of the prostate gland. "As such, POM121 promoted lethal prostate cancer through binding to importin-β, leading to nuclear import of oncogenic transcription factors (E2F1, MYC e.a.)." (PMID 38177114, 2024). "In mouse prostate cancer xenografts, POM121 drives tumor progression through importin-β-dependent nuclear import of androgen receptor, E2F1 and MYC, whereas importin-β inhibitor importazol attenuated tumor growth." (PMID 38177114, 2024). "POM121 enhances importin-dependent nuclear transport of oncogenic and prostate cancer-specific transcription factors, promoting prostate cancer aggressiveness." (PMID 35047516, 2021). "Targeting the POM121-importin β axis was proposed as a therapeutic strategy for lethal prostate cancer." (PMID 35047516, 2021). "POM121 was found to promote proliferation, aggressiveness, and therapeutic resistance in prostate cancer." (PMID 31528211, 2019). "POM121 is upregulated in prostate cancer, colorectal cancer, gastric cancer, and lung cancer." (PMID 40861463, 2025). "POM121 has been reported to be a key contributor to prostate cancer aggressiveness." (PMID 34257547, 2021). "POM121 regulates nuclear import of oncogenic MYC through importinβ to promote prostate cancer." (PMID 31528211, 2019).
lung carcinoma (4 papers, 2007 to 2025). "In lung cancer and GC, POM121 overexpression has been associated with abnormal activation of important signaling pathways, such as the TGF-β/SMAD and PI3K/AKT pathways." (PMID 39080077, 2024). "The expression levels of mRNA and protein of POM121 in colon cancer, oral squamous cell carcinoma, lung cancer, and laryngeal cancer tissues are also found to be higher than in adjacent tissues." (PMID 37409345, 2023). "While there are no reports of POM121 specifically associated with lung cancer or a neoplastic process of any kind, there are reports of increased expression of nuclear pore proteins in some cancer." (PMID 19455237, 2007). "In various cancer types, including CRC, lung cancer, laryngocarcinoma, PCa, GC, and oral SCC, the oncoprotein POM121 is universally overexpressed and plays a role in modulating key signaling pathways." (PMID 39080077, 2024).
amyotrophic lateral sclerosis (3 papers, 2021 to 2024). Amyotrophic lateral sclerosis (ALS) is a neurodegenerative disease characterized by progressive muscular paralysis reflecting degeneration of motor neurons in the primary motor cortex, corticospinal tracts, brainstem and spinal cord. "The reduction in POM121 was believed to result from expanded C9orf72 amyotrophic lateral sclerosis overlapping with frontotemporal dementia (ALS/FTD) repeat RNA alone." (PMID 39080077, 2024). "The mechanistic underpinnings of C9orf72 in cellular toxicity and ultimately neuronal degeneration dependent Amyotrophic Lateral Sclerosis and Frontotemporal Dementia (ALS/FTD) emphasized the pathologic effects of POM121 depletion downstream of G4C2 repeat RNA expression." (PMID 34970494, 2021).
cervical cancer (3 papers, 2018 to 2022). A primary or metastatic malignant neoplasm involving the cervix. "The identified proteins (AGR2, BRD7, and POM121) were differentially expressed according to cell type, clinical prognostic factors, and resistance to radiation therapy in cervical cancer patients." (PMID 30406031, 2018). "Furthermore, we demonstrated for the first time that low expression of AGR2, high expression of BRD7 or POM121 combined with low expression of PAUF predict delayed recurrence in cervical cancer patients." (PMID 30406031, 2018). "Furthermore, we demonstrated that AGR2, BRD7, and POM121 protein expression had prognostic value when combined with PAUF expression using an analysis of a large cohort of cervical cancer patients." (PMID 30406031, 2018). "In addition, the higher expression of AGR2 was negatively correlated with LVSI and the depth of invasion (p = 0.007 and p = 0.042, respectively), and POM121 expression was decreased (p = 0.001) in radiation-resistant cervical cancer." (PMID 30406031, 2018). "However, further research is needed to identify the accurate mechanism of POM121 in cervix carcinoma tumorigenesis." (PMID 30406031, 2018). "In our cervical cancer samples, low expression of POM121 alone was not correlated with decreased DFS." (PMID 30406031, 2018).
colorectal cancer (3 papers, 2021 to 2025). A primary or metastatic malignant neoplasm that affects the colon or rectum. "Overexpression of POM121 is associated with metabolic diseases (e.g., diabetes) and unfavorable clinical outcome in patients with colorectal cancer (CRC)." (PMID 38177114, 2024). "POM121 has also been linked as a potential prognostic biomarker in oral squamous cell carcinoma (OSCC), colorectal cancer (CRC), laryngeal cancer (LRC), and non-small-cell lung cancer (NSCLC), where elevated levels of POM121 are linked to advanced tumor-node-metastasis (TNM) stages." (PMID 34970494, 2021).
laryngeal carcinoma (3 papers, 2021 to 2024). Carcinoma that arises from the laryngeal epithelium. "Gene-set enrichment analyses in laryngeal cancer confirmed that POM121 relates to fatty acid metabolism and PPAR signaling." (PMID 38177114, 2024).
non-small cell lung carcinoma (3 papers, 2021 to 2025). A group of at least three distinct histological types of lung cancer, including non-small cell squamous cell carcinoma, adenocarcinoma, and large cell carcinoma. "In non-small cell lung cancer (NSCLC), lactylation at H3K18 activates the POM121/MYC/PD-L1 axis, leading to diminished CD8+ T-cell activity and enhanced immune evasion." (PMID 41373440, 2025).
acute lymphoblastic leukemia (2 papers, 2021 to 2022). Leukemia with an acute onset, characterized by the presence of lymphoblasts in the bone marrow and the peripheral blood. "POM121 fusion with PAX5 (a transcription factor critical in B-cell development) generates aberrant chimeric proteins in childhood acute lymphoblastic leukemia (ALL)." (PMID 34970494, 2021).
ovarian carcinoma (2 papers, 2022 to 2023). A malignant neoplasm originating from the surface ovarian epithelium. "The same trend of changes in the POM121, EDC4, and SNRPC genes was also found in ovarian cancer." (PMID 37409345, 2023).
breast carcinoma (1 paper, 2022). "A new target gene candidate of miR-129-5p, POM121 was searched through the biological website TargetScan, and its effect on the proliferation and invasion of breast cancer cells was evaluated." (PMID 35419056, 2022).
dysplasia (1 paper, 2019). A usually neoplastic transformation of the cell, associated with altered architectural tissue patterns. "We also detected POM121 expression in oral dysplasia tissues and confirmed that high POM121 was expressed in OSCC tissues but not dysplasia (22.00%)." (PMID 31528211, 2019).
HIV-1 infection (1 paper, 2023). The type species of lentivirus and the etiologic agent of acquired immunodeficiency syndrome (AIDS). "While depletion of POM121 had a more profound effect on WT HIV-1 infection, binding assays indicated interaction with N74D HIV-1 as well." (PMID 37355754, 2023). "Similar to Nup153 and CPSF6, TRIM5 fusions to the FG-rich portion of POM121 inhibit HIV-1 infection." (PMID 37355754, 2023). "Nup35, Nup153, Nup358, and POM121 depletion were observed to inhibit WT HIV-1 infection but affected N74D and P90A HIV-1 infection to a lesser degree." (PMID 37355754, 2023). "Indeed, in cells depleted of Nup35, POM121, or Nup153, a partial restoration of WT HIV-1 infection is observed after coordinate knockdown of CPSF6, especially in Nup35 and POM121 knockdown cells." (PMID 37355754, 2023). "Our data indicate that POM121 interaction with CA appears to support HIV-1 infection." (PMID 37355754, 2023). "Notably, depletion of CypA not only restored HIV-1 infection in Nup35-knockdown cells but similarly restored infection in POM121-knockdown cells and partly restored infection in Nup153-knockdown cells." (PMID 37355754, 2023). "Because Nup35 and POM121 depletion affected WT HIV-1 infection but not CA mutant HIV-1 in a pattern similar to Nup153 and Nup358, we focused efforts on these two Nups." (PMID 37355754, 2023).
Huntington disease (1 paper, 2023). Huntington disease (HD) is a rare neurodegenerative disorder of the central nervous system characterized by unwanted choreatic movements, behavioral and psychiatric disturbances and dementia. "Overexpression of SIGMAR1 or POM121, or treatment with the highly selective and potent SIGMAR1 agonist pridopidine, currently in phase 2/3 clinical trials for ALS and Huntington disease, rescues all of these deficits." (PMID 35507432, 2023).
leukemia (1 paper, 2024). A malignant (clonal) hematologic disorder, involving hematopoietic stem cells and characterized by the presence of primitive or atypical myeloid or lymphoid cells in the bone marrow and the blood. "In patients, POM121 is overexpressed in cancers of the upper gastrointestinal tract, the lungs and in CRC, and therein associated with higher tumor (TNM) staging, metastasis and poor prognosis, while POM121 gene fusions present in leukemia." (PMID 38177114, 2024).
lymph node metastasis (1 paper, 2019). "Kaplan-Meier survival curves confirmed that high POM121 expression, lymph node metastasis, distant metastases, and TNM stage were associated with poor OS and disease-free survival." (PMID 31528211, 2019). "Multivariate analysis further confirmed that POM121 expression, lymph node metastasis, and TNM stage were independent prognostic factors for OSCC patients." (PMID 31528211, 2019). "Multivariate analysis showed that high POM121 expression (HR, 1.844; 95% CI, 1.321-2.575; P<0.001) was an independent prognostic factor for OS, as well as lymph node metastasis (HR, 1.322; 95% CI, 1.053-1.659; P=0.016) and TNM stage (HR, 1.163; 95% CI, 1.017-1.331; P=0.028)." (PMID 31528211, 2019).
oral cancer (1 paper, 2019). "However, little is known about the relationship between POM121 and oral cancer." (PMID 31528211, 2019).
Parkinson disease (1 paper, 2020). A progressive degenerative disorder of the central nervous system characterized by loss of dopamine producing neurons in the substantia nigra and the presence of Lewy bodies in the substantia nigra and locus coeruleus. "For example, AD-related pathology is associated with a loss of LMNB, while knockdown of LMNB1, as well as the pore membrane protein of 121 kDa (POM121), increases α-synuclein aggregation in the nuclear envelope in early stages of apoptosis, with potential implications for Parkinson’s disease." (PMID 32630170, 2020).
triple-negative breast carcinoma (1 paper, 2020). An invasive breast carcinoma which is negative for expression of estrogen receptor (ER), progesterone receptor (PR), and human epidermal growth factor receptor 2 (HER2). "The POM121L2 gene codes for POM121 transmembrane nucleoporin like 2, which has been shown to be upregulated in triple negative breast cancer." (PMID 33113958, 2020).
cancer (8 papers, 2007 to 2024). A tumor composed of atypical neoplastic, often pleomorphic cells that invade other tissues. "POM121 has been linked to metabolic disease (e.g., fasting serum insulin) and lipid/carbohydrate metabolism in cancers by contributing to adipogenesis in human white fat tissues." (PMID 38177114, 2024). "Due to the association between chromosomal instability (CIN), nuclear structural aberrations and tumor progression, POM121 and other Nups have been linked to cancer." (PMID 38177114, 2024). "In summary, POM121 has been implicated in a wide range of cellular processes, from viral infection to cancer progression and neurodegeneration." (PMID 39080077, 2024). "This query collected supportive evidence for POM121 mRNA/protein variants due to alternative splicing and/or translation in large series of cancer cell lines (e.g., CCLE) and CRC patients (n = 13 studies)." (PMID 38177114, 2024). "Apart from acting as a gene fusion product, POM121 also contributes to cancer progression by mediating the transport of oncogenic molecules into the nucleus." (PMID 34970494, 2021). "Population-based fluorescence in situ hybridization (FISH) analysis demonstrated chromosomal translocation events involving the POM121 gene forming gene fusions leading to cancer." (PMID 34970494, 2021). "Since POM121 is frequently overexpressed in cancers including CRC, this post-translational inhibition of PPARγ may prevent its anti-proliferative, differentiation-promoting effects in tumor cells and also mitigate its modulatory function on metabolism and immunity." (PMID 38177114, 2024). "Overall, this PPI network analysis suggested that POM121 is connected to cell functions apart from NPC formation, such as transcriptional regulation (e.g., of nuclear “hormone” receptors) and the cancer immuno-microenvironment." (PMID 38177114, 2024). "A recent study on POM121 in NSCLC has provided insights into the involvement of TGF-β/SMAD and PI3K/AKT signaling pathways in cancer cell proliferation and metastasis." (PMID 34970494, 2021).
tumor (7 papers, 2019 to 2024). "We next asked if loss of POM121 affects the viability of tumor cells." (PMID 38177114, 2024). "Its interactome was predicted to include proteins responsible for tumor metabolism and immunity, and in-silico modeling provided insights into potential 3D structures of POM121." (PMID 38177114, 2024). "CIRCINTS4 knockdown prevents ADR-resistant tumor growth by regulating the miR-129-5p/POM121 axis in vivo." (PMID 35419056, 2022). "Univariate analysis indicated that POM121 expression (P<0.001), tumor size (P=0.039), lymph node status (P<0.001), distant metastasis (P=0.021), and TNM stage (P<0.001) were significantly associated with OS of OSCC patients." (PMID 31528211, 2019). "Univariate Cox regression analysis showed that POM121 expression, tumor size, lymph node status, distant metastasis, and TNM stage were associated with survival of OSCC patients." (PMID 31528211, 2019). "Notably, KRAS mutant cases with high POM121 protein positivity had more PPARγ protein localized to the peri-nuclear and cytoplasmic regions of the tumor cells compared with KRAS wt cases, who showed nuclear positivity of PPARγ (n = 208, *p < 0.05, Fisher Exact test)." (PMID 38177114, 2024). "Furthermore, POM121 expression increases with tumor progression, suggesting that POM121 may be a target molecule for patients with advanced PCa." (PMID 39080077, 2024). "POM121 may participate in tumor progression through these proteins." (PMID 31528211, 2019). "In this study, we analyzed POM121 expression in OSCC tissues and in oral non-tumor tissues and confirmed that POM121 expression was related to tumor proliferation, metastasis, and poor prognosis in OSCC." (PMID 31528211, 2019). "As for others, CTC, GIGYF1, MTUS2, POM121, PTP14, SPOPL, and ZNF 208 were detected only in tumor tissue, and none were determined to be pathogenic by both algorithms concordantly." (PMID 38254245, 2024). "Taken together, overexpression of POM121 in CRC may inhibit the transcriptional activity of PPARγ, thereby abrogating its tumor suppressor function, e.g., via the cell cycle inhibitor P21 CIP1/WAF1." (PMID 38177114, 2024). "We therefore hypothesized that POM121 participates in the transport of PPARγ across the NPC to regulate its transcriptional activity on genes involved in metabolic and tumor control." (PMID 38177114, 2024).
infection (3 papers, 2023 to 2024). The state of being infected such as from the introduction of a foreign agent such as serum, vaccine, antigenic substance or organism. "We first examined whether HIV-1 and MLV were differentially susceptible to infection in cells expressing the TRIM5a.POM121 fusion proteins." (PMID 37355754, 2023). "Interestingly, N74D CA-NC complexes bound to C-terminal POM121 as efficiently as WT CA-NC complexes, which is consistent with the infection block observed using TRIM5 fusion proteins." (PMID 37355754, 2023). "Further IFN and antiviral related proteins were upregulated upon infection with PeV-A3 (EIF2AK2, STAT1), or PeV-A1 (NCAM1, POM121), and downregulated upon PeV-A1 infection (EIF4G1, UBE2N, RANBP2, FLNA)." (PMID 38514653, 2024). "While HIV-1 was blocked for infection in Nup35 or POM121 knockdown cells, after treatment with CsA, HIV-1 enters the nucleus and infection is restored to levels of control cells." (PMID 37355754, 2023). "Whereas CsA treatment, predictably, does little to affect P90A infection in the POM121 or Nup153 knockdown cells, CPSF6 depletion potently enhances infection when in conjunction with either knockdown." (PMID 37355754, 2023). "Notably, 9 nucleoporins (NUP58, NUP214, NUP98, NUP54, NUP62, NUP88, NUP153, POM121/NUP121 and RANBP2/NUP358) and the mRNA export factor Rae1 were present in both the CebN infection and transfection interactomes." (PMID 38712050, 2024).
neurologic diseases (1 paper, 2024). "First, we examined markers for different compartments of the NPC which have been shown to been altered in neurologic diseases, including Nup62 and Nup98 in the central channel, POM121 to demarcate the transmembrane ring, and RanBP2 within the cytoplasmic ring and filaments." (PMID 39452051, 2024).
POM121 also shares sentences with these, for which no sentence is quoted: oral squamous cell carcinoma (3 papers); frontotemporal dementia (2); breast tumor (1); colon cancer (1); diabetes (1); diffuse large B-cell lymphoma (1); escherichia coli infection (1); esophageal squamous cell carcinoma (1); gastric cancer (1); hematological malignancies (1); melanoma (1); metabolic disease (1); mucosal melanoma (1); Salmonella Infections (1); Williams-Beuren Syndrome (1).